GBA2 (glucosylceramidase beta 2)
Description:
Non-lysosomal glucosylceramidase that catalyzes the hydrolysis of glucosylceramides/GlcCers (such as beta-D-glucosyl- (1<->1')-N-acylsphing-4-enine) to free glucose and ceramides (such as N-acylsphing-4-enine). GlcCers are membrane glycosphingolipids that have a wide intracellular distribution (By similarity). They are the main precursors of more complex glycosphingolipids that play a role in cellular growth, differentiation, adhesion, signaling, cytoskeletal dynamics and membrane properties (By similarity). Involved in the transglucosylation of cholesterol, transfers glucose from GlcCer to cholesterol, thereby modifying its water solubility and biological properties. Under specific conditions, may catalyze the reverse reaction, transferring glucose from cholesteryl-3-beta-D-glucoside to ceramide (such as N-acylsphing-4-enine) (Probable). May play a role in the metabolism of bile acids. Able to hydrolyze bile acid 3-O-glucosides as well as to produce bile acid-glucose conjugates thanks to a bile acid glucosyl transferase activity. Catalyzes the hydrolysis of galactosylceramides/GalCers (such as beta-D-galactosyl-(1<->1')-N-acylsphing-4-enine), as well as the galactosyl transfer between GalCers and cholesterol in vitro with lower activity compared with their activity against GlcCers.
Synonyms: NLGase; KIAA1605; SPG46; AD035; DKFZp762K054
Tractability: Small molecule: a high-quality ligand is known; it belongs to a druggable protein family. Antibody: UniProt places it where antibodies can reach, with high confidence; its Gene Ontology location is reachable by antibodies, with high confidence. PROTAC: ubiquitination databases record sites on it; its protein half-life has been measured; a small molecule that binds it is known.
Target class: Enzyme
Gene: Protein-coding gene on chromosome 9 (35,736,864 to 35,749,986, reverse strand). Ensembl gene ENSG00000070610.
Subcellular location: Endoplasmic reticulum membrane; Golgi apparatus membrane
Subcellular location (Human Protein Atlas): Golgi apparatus; Nucleoplasm; Cytosol
Pathways (Reactome):
Metabolism: Glycosphingolipid catabolism
Gene Ontology:
Molecular function: beta-glucosidase activity; glucosylceramidase activity; glucosyltransferase activity; steryl-beta-glucosidase activity; galactosylceramidase activity; hydrolase activity, hydrolyzing O-glycosyl compounds
Biological process: bile acid metabolic process; central nervous system neuron development; glucosylceramide catabolic process; glycoside catabolic process; central nervous system development; cholesterol metabolic process; glycolipid biosynthetic process; glycosphingolipid catabolic process; regulation of actin filament polymerization; regulation of membrane lipid distribution; regulation of microtubule polymerization; carbohydrate metabolic process; sphingolipid metabolic process; steroid metabolic process
Cellular component: membrane; cytosol; endoplasmic reticulum membrane; Golgi membrane; plasma membrane; smooth endoplasmic reticulum; endoplasmic reticulum
Genetic constraint (gnomAD): Loss-of-function variants: 64 observed, 101.92 expected, observed/expected ratio (o/e) 0.63, 90% interval 0.51 to 0.77. The upper end of that interval is the gene's LOEUF score, 0.77, which puts it in group 3 of 6, group 1 being the genes least tolerant of losing a copy. Missense variants: 978 observed, 1,157.5 expected, observed/expected ratio (o/e) 0.84, 90% interval 0.8 to 0.89. Synonymous variants: 379 observed, 428.52 expected, observed/expected ratio (o/e) 0.88, 90% interval 0.81 to 0.96.
Gene-disease validity (ClinGen):
ClinGen rates the evidence that GBA2 causes each of these diseases.
complex hereditary spastic paraplegia (autosomal recessive): Definitive. A hereditary spastic paraplegia that is part of a larger syndrome.
Homologues: Orthologues: chimpanzee GBA2 (99% identical), macaque GBA2 (97% identical), dog GBA2 (90% identical), rabbit GBA2 (88% identical), guinea pig GBA2 (87% identical), rat Gba2 (87% identical), mouse Gba2 (87% identical), pig GBA2 (87% identical), zebrafish gba2 (60% identical), tropical clawed frog GBA2 (52% identical), Drosophila melanogaster CG33090 (40% identical), Caenorhabditis elegans hpo-13 (36% identical), and 1 more.
Diseases named in the same sentence as GBA2 in open-access papers:
GBA2 is named in the same sentence as 60 diseases in open-access papers, as found by Europe PMC text mining. Sharing a sentence is not in itself a finding about the gene and the disease. The quoted sentences say what the papers report.
Ataxia (13 papers, 2015 to 2024). Ataxia refers to impaired coordination of voluntary muscle movement. "GBA2 deficiency is responsible for a heterologous group of ataxias, including hereditary spastic paraplegia (HSP), autosomal recessive cerebellar ataxia (ARCA) with spasticity and Marinesco-Sjogren-like syndrome." (PMID 33261081, 2020). "Mutations in the GBA2 gene are associated with two neurological diseases on the ataxia-spasticity spectrum, hereditary spastic paraplegia 46 (SPG46) and Marinesco-Sjögren-like syndrome (MSS)." (PMID 32492073, 2020). "Mutations in the human GBA2 gene result in diseases on the ataxia-spasticity spectrum, cerebellar ataxia/hereditary spastic paraplegia 46 (SPG46) and Marinesco-Sjögren-like syndrome (MSS)." (PMID 32492073, 2020). "We have also established that nonsense and missense mutations in the GBA2 gene associated with cerebellar ataxia/spastic paraplegia abolish most of its enzyme activity." (PMID 32492073, 2020). "In contrast, humans carrying mutations in the GBA2 gene are affected with cerebellar ataxia with spasticity or spastic paraplegia (Spastic Gait locus #46, SPG46)." (PMID 33261081, 2020). "In 2018, a Norwegian group identified a homozygous deletion mutation in GBA2 (p.M510Vfs*17) in families with Marinesco-Sjogren syndrome and the patients presented with ataxia, early-onset cataracts, hypotonia and muscle weakness." (PMID 31289639, 2019). "GBA2 mutations have been described in families manifesting complex early onset recessive phenotypes usually involving spasticity, but also ataxia and peripheral nerve involvement." (PMID 28052128, 2017). "The overlap between HSP and ataxias was again recently highlighted by mutations in GBA2 (SPG46), which have been found in patients with spastic ataxia associated with cataract, having ataxia or spasticity as the prominent clinical feature." (PMID 25758904, 2015). "In cells, glucosylceramide is also degraded outside lysosomes by the enzyme glucosylceramidase 2 (GBA2) of which inherited deficiency is associated with ataxias." (PMID 26418157, 2015). "Furthermore, one missense and three truncated GBA2 variants were identified in the genome of patients suffering from HSP accompanied by cerebellar ataxia." (PMID 29234271, 2017). "The relative high expression of GBA and GBA2 in neuronal cells in specific motor areas of the brain seems to correlate with motor related neurological disorders associated with their deficiencies such as Parkinson disease and cerebellar ataxia, respectively." (PMID 26418157, 2015). "For example, pathogenic variants in the ceramide synthase gene CERS2 cause epilepsy and ataxia, and mutations in genes involved in sphingolipid metabolism such as B4GALNT1, GBA2, and even FA2H, cause different forms of spasticity and ataxia, such as SPG26, SPG46, and SPG35, respectively." (PMID 38911600, 2024). "Inhibition of GBA2 in GD and NPC patients treated with N-butyldeoxynojirimycin causes no major complications, whereas on the other hand, individuals with spastic paraplegia and cerebellar ataxia were found to be GBA2 deficient." (PMID 32182893, 2020). "The clinical syndrome associated with GBA2 mutations was characterized either as an autosomal recessive cerebellar ataxia (ARCA) with spasticity or complicated hereditary spastic paraplegia (HSP) with ataxia: the latter is also known as spastic paraplegia 46 [SPG46 (MIM #614409)]." (PMID 28052128, 2017). "At times, the differentiation between cerebellar ataxia and HSP seems artificial, as it reveals a phenotypic continuum linked to specific genes, which can be better understood through the concept of variable expressivity: indeed, little is known about any cis–trans regulatory elements of GBA2." (PMID 38334933, 2024). "Specifically, GBA2 is shown to interact with ASAH1 protein, which is over-expressed at the mRNA level in both neuronal “ataxia” datasets and peripheral blood “ataxia” datasets." (PMID 32937819, 2020).
Ataxia (continued). "In conclusion, ABPs offer sensitive tools to visualize active GBA and to study the distribution of GBA2 in the brain and thus may find application to establish the role of these enzymes in neurodegenerative disease conditions such as α-synucleinopathies and cerebellar ataxia." (PMID 26418157, 2015). "GBA2 has been noted to be under expressed in neurons in ataxia datasets, although alternative splicing was not considered." (PMID 33261081, 2020).
Gaucher disease (10 papers, 2013 to 2024). Gaucher disease (GD) is a lysosomal storage disorder encompassing three main forms (types 1, 2 and 3), a fetal form and a variant with cardiac involvement (Gaucher disease - ophthalmoplegia - cardiovascular calcification or Gaucher-like disease). "A variant in GBA has been shown to cause alternative splicing leading to Gaucher disease, so the possibility of GBA2 mutations leading to over production of inactive isoforms should be considered." (PMID 33261081, 2020). "In fact, concomitant loss of GBA2 activity in a GBA1-mouse model for Gaucher disease rescued the clinical phenotypes although glycosphingolipid levels were increased." (PMID 29234271, 2017). "Furthermore, loss of GBA1 activity down-regulated GBA2 activity in fibroblasts from patients with Gaucher disease." (PMID 29234271, 2017). "Our studies show that a reduced activity of GBA2 is sufficient to elevate the levels of glucosylceramide to similar levels as seen in Gaucher disease." (PMID 28052128, 2017). "Beyond that, our results in the genetic approach, i.e. the identification of an epistatic effect involving p.L444P and a marker at the GBA2 locus, point to a potential role of GBA2 as a modifier mainly for type 2 and 3 Gaucher disease." (PMID 24070122, 2013). "Our functional results all together provide further evidence for the involvement of GBA2 as a likely candidate in the etiology of Gaucher disease." (PMID 24070122, 2013). "Independent studies are warranted to follow up on our interaction finding and to further investigate the role of GBA2 in the clinical expression of Gaucher disease." (PMID 24070122, 2013). "We examined the potential role of GBA2 as a modifier of Gaucher disease and the crosstalk between GBA1 and GBA2 using three subsequent steps." (PMID 24070122, 2013). "These properties may be useful to facilitate the research on the role of GBA2 and GBA3 in Gaucher disease and other disorders." (PMID 39305182, 2024). "In the present study, we explored whether the non-lysosomal glucocerebrosidase (GBA2) could play a role as modifier for Gaucher disease." (PMID 24070122, 2013).
autosomal recessive cerebellar ataxia (7 papers, 2017 to 2024). "Mutations in GBA2 have been associated with the development of neurological disorders such as autosomal recessive cerebellar ataxia, hereditary spastic paraplegia, and Marinesco-Sjogren-Like Syndrome." (PMID 30308956, 2018). "GBA2 mutations seem to lead to a clinical spectrum that encompasses different phenotypes, including HSP, autosomal recessive cerebellar ataxia (ARCA), or a more complex and severe condition like Marinesco-Sjögren Syndrome (MSS)." (PMID 38334933, 2024). "Homozygous loss of function GBA2 mutations are responsible for hereditary spastic paraplegia (HSP; SPG46), autosomal-recessive cerebellar ataxia (ARCA) and Marinesco-Sjögren-like syndrome in humans." (PMID 33971917, 2021). "Mutations in the human GBA2 gene have been associated with hereditary spastic paraplegia (HSP) and autosomal-recessive cerebellar ataxia (ARCA)." (PMID 29234271, 2017).
hereditary spastic paraplegia (7 papers, 2017 to 2022). Hereditary spastic paraplegias (HSP) comprise a genetically and clinically heterogeneous group of neurodegenerative disorders characterized by progressive spasticity and hyperreflexia of the lower limbs. "On the contrary, GBA2-knockdown zebrafish show abnormal motor neuron development, and mutations in the human GBA2 gene have been found to lead to neurological disorders like spastic ataxia (SA), hereditary spastic paraplegia (HSP), and more recently Marinesco-Sjogren-Like Syndrome." (PMID 30308956, 2018). "In contrast to these cases where knocking down GBA2 activity is desired, mutations that knock out GBA function lead to hereditary spastic paraplegia, autosomal recessive ataxia with spasticity and Marinesco-Sjogren-Like Syndrome." (PMID 33261081, 2020).
Parkinson disease (7 papers, 2015 to 2025). A progressive degenerative disorder of the central nervous system characterized by loss of dopamine producing neurons in the substantia nigra and the presence of Lewy bodies in the substantia nigra and locus coeruleus. "It should be noted there is no report that Miglustat (N-butyldeoxynojirimycin), an orphan drug for type 1 GD disease or NPC, which inhibits GBA2 activity as well as glucosylceramide synthase, induced parkinsonism." (PMID 33971917, 2021). "However, most GBA2 inhibitors are in development for Parkinson’s disease: ALU1811 is in preclinical development by Biogen and Alectos for Parkinson’s disease, and the GCS and GBA2 inhibitor nizubaglustat is in development for PD." (PMID 41227379, 2025). "Pharmacological inhibition of GBA2 by N-alkyl iminosugars is well tolerated and benefits patients suffering from Sandhoff and Niemann–Pick type C diseases, and GBA2 inhibitors have been proposed as candidate-clinical drugs for the treatment of parkinsonism." (PMID 39246358, 2024). "Specifically, it has been shown that the activity of GBA and GBA2 progressively decrease in the substantia nigra with normal ageing and are further decreased in Parkinson’s disease (PD), followed by accumulation of glucosylceramide, which is the natural substrate of glucosylceramidases." (PMID 35277195, 2022).
melanoma (5 papers, 2015 to 2025). A malignant, usually aggressive tumor composed of atypical, neoplastic melanocytes. "It has been shown that inducing GBA2 expression would promote glucosylceramide hydrolysis and impair melanoma growth ina mouse xenograft model." (PMID 40636215, 2025). "GBA2 also has been shown to function as a tumor suppressor in melanoma cells and cholangiocarcinoma." (PMID 38260847, 2023). "Of note, excessive formation of ceramide by GBA2 has recently been reported to promote apoptosis in human melanoma cells." (PMID 26275242, 2015). "Of note, GBA2 gene is downregulated in melanoma cells as compared to melanocytes." (PMID 32858889, 2020). "Three genes (CYP3A4, GBA2 and PTK6) were identified to besignificantly downregulated in melanoma patients." (PMID 40636215, 2025). "The anti-melanoma effect of S. nigrum is likely through the modulation of three unique melanoma-related gene targets(CYP3A4, GBA2 and PTK6) by its two unique active ingredients (diosgenin and solanocapsine)." (PMID 40636215, 2025).
Globozoospermia (4 papers, 2015 to 2021). Any structural anomaly of the acrosome resulting in a round sperm head. "Such differential effects of GBA2 loss between medaka and mice are seen also in spermatogenesis, as Gba2 KO mice show infertility due to morphological abnormality of sperm, called globozoospermia, while gba2 KO medaka showed a normal fertilization rate." (PMID 33971917, 2021). "β-Glucosidase 2 (GBA2) is a glycolipid hydrolase resident in ER and its relation to globozoospermia was first recognized in glycolipid storage disease due to deficiency of Gba2 in male mice with reduced fecundity." (PMID 30291685, 2019). "Accumulation of GlcCer in GBA2 knockout-mice has been proposed to underlie the defects in spermatogenesis leading to globozoospermia." (PMID 25803043, 2015). "The predominant phenotype associated with the genetic loss of GBA2 in a mouse model was observed in male reproduction: male GBA2 knockout mice were subfertile due to a sperm morphological defect occurring during spermatogenesis, a condition called globozoospermia." (PMID 29234271, 2017). "Here, we demonstrate that cytoskeletal dynamics controlling sperm-head shaping and acrosome formation are affected by accumulation of GlcCer in GBA2 knockout-mice, which results in globozoospermia and, thereby, male infertility." (PMID 25803043, 2015). "Unlike in mice, mutational assessments for GBA2 in 3 unrelated families, originating from Britain, Canada, and Germany, have been unfruitful to show an association with globozoospermia in man." (PMID 30291685, 2019). "Knockout mice approach for different purposewhich later exhibited globozoospermia manifestation.The target genes were as: Csnk2a2, GOPC, Gba2,PICK1, iii." (PMID 30291685, 2019). "Accumulation of GlcCer due to the lack of GBA2 activity induces actin polymerization and microtubule persistence, resulting in globozoospermia and male infertility." (PMID 25803043, 2015). "Sperm from GBA2 knockout-mice display globozoospermia: the heads are round rather than sickle-shaped and the acrosome is malformed." (PMID 25803043, 2015).
spastic ataxia (4 papers, 2013 to 2020). "Our group has previously published the GBA2 c.1780G > C (p.Asp594His) missense variant as the cause of spastic ataxia in a Cypriot consanguineous family, and more recently the biochemical characterization of this variant in patients’ lymphoblastoid cell lines." (PMID 32937819, 2020). "We have previously identified a GBA2 missense mutation [c.1780G>C (p.Asp594His)] in a Cypriot family with progressive spastic ataxia." (PMID 30308956, 2018). "Among them, a c.1780G>C (p.Asp594His) missense mutation located in exon 11 of the GBA2 gene was identified in a Cypriot consanguineous spastic ataxia family." (PMID 30308956, 2018). "In the present study we have undertaken the biochemical characterization of the GBA2 c.1780G>C missense mutation in lymphoblastoid cell lines (LCLs) derived from spastic ataxia patients homozygous for the mutation." (PMID 30308956, 2018). "Our group has previously identified the GBA2 c.1780G>C [p.Asp594His] missense mutation, in a Cypriot consanguineous family with spastic ataxia." (PMID 30308956, 2018). "However, in humans GBA2 gene mutations are found in spastic ataxia and spastic paraplegia patients (SPastic Gait locus #46, SPG46)." (PMID 30308956, 2018). "Thus, ARSACS should be part of the differential diagnosis in spastic ataxias with TCC, like e.g. SPG11, SPG15 or GBA2." (PMID 23497566, 2013).
Synucleinopathies (4 papers, 2015 to 2022). "The upregulation of GBA2 in NP-C caused defects in sphingolipid targeting from ER to Golgi and lysosomal pH adjustment, whereas the downregulation of GBA2 in PD was associated with synucleinopathy, which was closely related to autophagic dysfunction." (PMID 35420383, 2022). "Further studies are required to determine whether GBA2 could be a therapeutic target of α-synucleinopathy." (PMID 33971917, 2021).